APP (amyloid beta precursor protein)
Diseases named in the same sentence as APP in open-access papers (continued):
Sharing a sentence is not in itself a finding about the gene and the disease.
Alzheimer disease (continued). "Although the amyloidogenic APP processing pathway has recently been targeted in patients with Alzheimer’s disease, the physiological role of APP/Aβ remains unclear, which limits our understanding of how such interventions could influence brain functions in health and disease." (PMID 33926999, 2021). "Taken together with our previous findings in APP- and tau-Tg mice, the present results suggest that nasal rifampicin could be a promising remedy for the prevention of neurodegenerative dementia including Alzheimer’s disease, frontotemporal dementia, and DLB." (PMID 34445158, 2021). "Calmodulin-like skin protein (CLSP), a secreted peptide, inhibits neuronal death in cell-based Alzheimer’s disease (AD) models and transgenic overexpression of the CLSP gene suppresses synaptic loss and memory impairment in AD model mice, APPswe/PS1dE9 double transgenic mice (APP/PS1 mice)." (PMID 33441550, 2021). "Fitting into this hypothesis, an increased expression of APP, an accumulation of Aβ peptides in the brain and reduced concentrations of Aβ peptides in the CSF were not only observed in patients with Alzheimer's disease but also with meningitis and other inflammatory diseases." (PMID 33013850, 2020). "However, in neurodegenerative diseases such as Alzheimer’s disease, miR-17-5p expression is inhibited and this may be responsible for an increase in APP protein levels." (PMID 33302351, 2020). "Furthermore, a recent hypothesis also suggests that synaptic dysfunction in Alzheimer’s disease is triggered by impairment of APP metabolism which further progresses via tau pathology." (PMID 32954296, 2020). "Thus, regulating the microdomain localization of APP could offer a new therapeutic strategy for Alzheimer’s disease." (PMID 33255194, 2020). "Finally, AAV9‐siRNA‐caspase‐1 was injected into the tail vein of APP/PS1 double transgenic mice (Alzheimer's disease mice) for caspase‐1 mRNA inhibition, followed by observation of behavioural changes in mice and measurement of the expression of inflammatory factors and pyroptosis‐related protein." (PMID 32521573, 2020). "A small proportion of AD cases have a genetic origin, classified as Familiar Alzheimer Disease (FAD), caused by mutations in the APP, Presenilin 1 or Presenilin 2 genes." (PMID 31920626, 2019). "Lower sAPPα levels have been found in cerebro-spinal fluid of Alzheimer’s disease patients carrying the Swedish mutations in APP and in post mortem brain, but pre-mortem studies in cerebro-spinal fluid or blood in patients with sporadic Alzheimer’s disease have not provided consistent results." (PMID 30612335, 2019). "In summary, although the involvement of Lrp1 in APP and amyloid β processing and Alzheimer’s disease pathogenesis is undeniable, given the complexity of interactions, their true nature may be hidden by the variability in cell lines and the systems used, and is still yet to be fully unraveled." (PMID 30931303, 2019). "In animal studies, beta-amyloid peptides such as APP (amyloid beta precursor protein) was shown to enhance SNCA (∝-synuclein) accumulation leading to neuronal deficits in a transgenic mouse model linking neurodegenerative diseases such as Alzheimer’s disease and Parkinson’s disease." (PMID 31092860, 2019). "Furthermore, Fbs1 attenuates amyloid-β (Αβ) production through ubiquitination of β-secretase (BACE1) and amyloid precursor protein (APP), and the expression of Fbs1 decreases in the brains of Alzheimer’s disease (AD) patients and Tg2576 mice, a well-characterized model of AD." (PMID 30837888, 2019). "However, it is unclear whether changes in glycan structure would alter cellular localization and processing pathways of APP and other glycoproteins involved in Alzheimer’s disease in a similar manner." (PMID 30054538, 2018).
Alzheimer disease (continued). "The Dominantly Inherited Alzheimer Network (DIAN) is an international observational study of APP, PSEN1, and PSEN2 mutation carriers with the goal of determining the sequence of changes in presymptomatic mutation carriers who are destined to develop Alzheimer disease." (PMID 30045758, 2018). "Indeed, restoration of memory deficits in 5XFAD and APP/PS1 mouse models of Alzheimer’s disease (AD) have been shown after both acute and chronic administration of DHF, while it did not seem to exert this effect when injected chronically in APP23PS45 transgenic mice." (PMID 29961124, 2018). "Such favorable positioning of the AUG encoding Met671 of APP was the basis for a proposal by Breimer and Denny that in Alzheimer’s disease the C99 APP fragment may be generated independently from βAPP by the internal initiation of translation of the intact βAPP mRNA." (PMID 29865246, 2018). "These new mechanistic insights into the role of triplication of genes on chromosome 21, other than APP, in the development of Alzheimer’s disease in individuals who have Down syndrome may have implications for the treatment of this common cause of neurodegeneration." (PMID 29945247, 2018). "Interestingly, insulin administered by intranasal improved cognitive dysfunction and insulin signaling, reduced amyloid-β (Aβ) production and amyloid plaque burden, and increased neurogenesis in 4-month-old APP/PS1 mice showing early Alzheimer's disease (AD) pathologies." (PMID 29850612, 2018). "Since β-amyloid is produced physiologically from amyloid-β protein precursor (APP) by most cells but particularly by neurons, it is thought that abnormal processing of APP in neurons results in the abnormal β-amyloid formation that characterizes Alzheimer’s disease." (PMID 30583484, 2018). "It remains also unclear whether the accumulation of APP‐CTFs is a general phenomenon in Alzheimer's disease and how APP‐CTFs would trigger or add to neurodegeneration, although various signaling pathways, some affecting neurite growth and dendritic arborization, have been proposed." (PMID 28588032, 2017). "Although amyloid β (Aβ) is fundamental to Alzheimer’s disease (AD) pathology development, Aβ-lowering drugs failed in clinical trials, suggesting that additional amyloid precursor protein (APP)-dependent mechanisms might play an important role in AD pathogenesis." (PMID 28374012, 2017). "In detail, under physiological conditions, these isoenzymes modulate the generation of amyloid precursor protein (APP), promoting the α-secretase activity therefore decreasing the production of amyloid-β proteins, which are the main macromolecular structures involved in Alzheimer’s disease." (PMID 28524095, 2017). "Sequential regulated proteolysis of APP by different secretases results in multiple break-down products including soluble ectodomains, the Aβ-peptides forming the amyloids in Alzheimer’s disease, and the APP intracellular domain (AICD) that is released into the cytosol." (PMID 28553201, 2017). "Therefore, repurposing US9 to track/modify these molecular events represents a valid approach to investigate pathological states including Alzheimer’s disease and HIV-associated neurocognitive disorders where APP misprocessing to amyloid beta formation has been observed." (PMID 29118375, 2017). "Thus, APP might serve as a common therapeutic target against Alzheimer's Disease (AD) and a host of other neurodegenerative diseases characterized by abnormal levels of Aβ and/or Tau." (PMID 28696204, 2017). "Finally, we show that Fraction 0–4 provides broad neuroprotection in organotypic brain slice models for neurodegeneration driven by amyloid precursor protein (APP) and tau implicated in Alzheimer’s disease and frontotemporal dementias, respectively, in addition to ischemic injury modeled by OGD." (PMID 27172999, 2016).
Alzheimer disease (continued). "Our results suggest that although no chemical inhibitors have been designed with the specific goal of targeting APLP2, existing beta-secretase inhibitors that have been made to target APP for the treatment of Alzheimer's disease may potentially be repurposed to target APLP2." (PMID 26840089, 2016). "However, our recent work has shown that the amyloid precursor protein (APP), a central molecule in Alzheimer's disease, binds to the VAC14 scaffold of the complex and enhances the activity of the PIKfyve complex in cells, providing a specific activator of this important enzyme complex." (PMID 26934981, 2016). "Finally, we show that PIKfyve activity is required for successful sorting of APP at endosomal membranes, establishing a complex and reciprocal relationship between APP and PIKfyve with interesting implications for our understanding of Alzheimer’s disease." (PMID 26216398, 2016). "Furthermore, its upregulation leads to phosphorylation of the amyloid precursor protein (APP) and tau, both associated with the pathological processes that lead to the hallmarks of Alzheimer’s disease (AD), i.e. Aβ-plaques and neurofibrillary tangles, respectively." (PMID 27429752, 2016). "Proteolytic processing of the Amyloid Precursor Protein (APP) produces beta-amyloid (Aβ) peptide fragments that accumulate in Alzheimer's Disease (AD), but APP may also regulate multiple aspects of neuronal development, albeit via mechanisms that are not well understood." (PMID 27932950, 2016). "Alzheimer's disease is characterized by the deposition of two distinct types of aggregates—extracellular plaques composed of Aβ peptides (cleavage products of the transmembrane protein APP) and intracellular neurofibrillary tangles composed of hyperphosphorylated tau protein." (PMID 25926130, 2015). "Moreover, we show that both Syt-1 and Syt-9 increase Aβ levels likely via BACE1-mediated APP processing and thus may play an important role in Alzheimer’s disease pathology." (PMID 26202512, 2015). "Alzheimer's disease (AD) is a neurodegenerative disease pathologically characterized by the deposition of the amyloid beta (Aβ) fragments derived from amyloid precursor protein (APP) in senile plaques and the accumulation of neurofibrillary tangles composed of tau protein." (PMID 26539559, 2015). "The observations in transgenic APP/PS1 mice, suggest that such homeostatic mechanism is disturbed by the presence of mutated APP and/or PS1, and may be relevant in Alzheimer's disease, as suggested by the generalized observation that DHA contents are reduced in the hippocampus of AD brains." (PMID 26257655, 2015). "Alzheimer's disease has two pathological hallmarks: intracellular neurofibrillary tangles, made up of aberrantly phosphorylated tau protein and plaques, made up of amyloidogenic (aberrant) processing of the amyloid precursor protein (APP), that leads to Aß peptide." (PMID 25324780, 2014). "LXR signalling impacts the development of Alzheimer’s disease (AD) pathology and LXRs are promising therapeutic targets for AD treatment because of their ability to affect components of the disease such as cholesterol content, Aβ clearance, APP processing, ABCA1, etc.." (PMID 25229406, 2014). "The existence of Aβ-like fragments of mEpCAM is described for the first time in the present study and might add up to a potential role for this part of the protein, possibly in conjunction with the cleavage through BACE1, as was extensively described for APP in Alzheimer’s disease." (PMID 24009667, 2013). "Moreover, by showing that APP plays an important role in normal axonal outgrowth, the study focuses attention of whether that role is compromised in Alzheimer's disease, for instance in hippocampal neurons, whose growth is essential for new memory formation." (PMID 23690749, 2013). "BACE1 or APP may conceivably contribute to Aβ in sporadic Alzheimer's disease cases." (PMID 23339066, 2013).
Alzheimer disease (continued). "Finally, although we have focused in this article only on APP and Aβ in the context of Alzheimer’s disease, the implication of a potential “airbag problem” for bench-to-bedside translational efforts is not restricted to research on this protein and its derivatives nor to AD-research only." (PMID 24252346, 2013). "Optical recordings of B103 rat neuroblastoma cells transfected with APP and loaded with Fluo-4AM showed an increase in intracellular Ca2+ levels in response to incubation with amyloid beta (Aβ), an APP-derived toxic peptide accumulating in brains of Alzheimer’s disease patients." (PMID 24330678, 2013). "In Alzheimer’s disease (AD), the combination of increased copper and Aβ [the amyloidogenic cleavage product of the amyloid precursor protein (APP)] in the synaptic cleft may promote the formation of neurotoxic Aβ-copper oligomers contributing to the neuropathology of AD." (PMID 23986700, 2013). "Thus finding compounds that interfere with dimerization of the APP ectodomain and increase the α-cleavage of APP could lead to the development of new therapies for Alzheimer's disease." (PMID 22768208, 2012). "Thus, changes in the regulation of retinal APP could contribute to the visual disturbances reported in patients with Alzheimer's disease." (PMID 22279552, 2012). "Mutations in amyloid-beta precursor protein (APP), presenilin 1 and 2 (PSEN1, PSEN2) are known to cause early onset (<60 years) familial Alzheimer disease (AD)." (PMID 22312439, 2012). "Alzheimer's disease (AD) is characterized pathologically by the presence of brain amyloid plaques and neurofibrillary tangles, the principle components of which are the amyloid precursor protein (APP) proteolytic cleavage product Aβ and the axonal microtubule associated protein Tau." (PMID 22272245, 2012). "Therefore, neuronal RAP by modulating LRP function and the uptake and processing of APP into beta amyloid could play a role in the overall modulation of the beta amyloid peptide burden of normal and Alzheimer's disease brain." (PMID 21152174, 2010). "In addition to intracellular tau inclusions, Alzheimer's disease brains also contain extracellular aggregates of amyloid β (Aβ) protein, derived via proteolysis from the larger transmembrane amyloid precursor protein (APP)." (PMID 20927324, 2010). "The lentiviral approach used in the present study could similarly be used to examine the effects of aging on the toxicity of mutant proteins involved in other neurodegenerative diseases (e.g. PS1/APP for Alzheimer's disease, and DJ-1, PINK-1, and LRRK2 for Parkinson's disease)." (PMID 19247483, 2009). "The peptide and its precursor (APP) play important roles in neuronal functions; thus, control of physiological A-Beta levels, rather than complete inhibition seems to be an important strategy to reduce the accumulation of neuritic plaques and thus slowing down the progression of Alzheimer's disease." (PMID 18682830, 2008). "Research on these inherited forms of Alzheimer disease has helped in the understanding of how plaques accumulate, which has subsequently led to new potential approaches to the treatment of Alzheimer disease such as lowering the production of Aβ from APP or enhancing clearance of the plaques." (PMID 17760499, 2007). "The γ-secretase complex is a membrane-embedded protease essential for intramembrane cleavage of substrates such as Notch receptors and the amyloid precursor protein (APP), processes central to cancer progression and Alzheimer's disease (AD) pathology." (PMID 41927485, 2026). "Amyloid-β (Aβ) protein, a cleavage product of the amyloid precursor protein (APP), is the main component of neuritic plaques in Alzheimer's disease (AD), and its accumulation has been considered as the molecular driver of Alzheimer's pathogenesis." (PMID 42123557, 2026).
Alzheimer disease (continued). "Accumulation of Amyloid β (Aβ), a peptide derived from endocytic processing of the amyloid precursor protein (APP), is a critical initial step in the development of Alzheimer's disease (AD)." (PMID 41816611, 2026). "We demonstrate that CRMP2 regulates mitochondrial PTP induction in APP-SAA knock-in mice, a mouse model of Alzheimer’s disease, through phosphorylation-dependent binding to the ANT." (PMID 41597254, 2026). "Lastly, HFD APP/PS1 mice demonstrate elevated cognitive deficits, neuroinflammation, and Alzheimer’s disease markers such as amyloid-β." (PMID 40819297, 2026). "We used adeno‐associated virus (AAV) to increase its expression in hippocampal astrocytes of APP/PSEN1 mice, an animal model for Alzheimer's disease (AD)." (PMID 39935382, 2025). "The consistently higher SBP in APP/PS1 mice, both at a young age and longitudinally post-surgery, highlights the potential impact of Alzheimer’s disease pathology on the cardiovascular system." (PMID 40141679, 2025). "In Alzheimer’s disease, MT5-MMP exhibits pro-amyloidogenic activity, functioning as an η-secretase that cleaves amyloid precursor protein (APP), ultimately generating two synaptotoxic fragments, Aη-α and Aη-β." (PMID 40867559, 2025). "It has also been found that in APP/PS1 transgenic mice, AEP activity was elevated during the early stages of Alzheimer’s disease—prior to the appearance of senile plaques and cognitive decline." (PMID 40722590, 2025). "For instance, in Alzheimer’s disease, the accumulation of APP/C99 at MAMs enhances ER–mitochondria tethering and ROS generation, both of which contribute to mitochondrial dysfunction." (PMID 41375524, 2025). "In Alzheimer’s disease, CRISPR-Cas9 reduces β-amyloid deposition by knocking out APP and PSEN1 genes, alleviating neuroinflammation and improving cognitive function." (PMID 40255230, 2025). "It cleaves amyloid precursor protein (APP) in vitro, reducing secretion of Aβ peptide, the molecular driver of Alzheimer's disease (AD)." (PMID 41015904, 2025). "Our findings highlight the functional excitation–inhibition ratio as a promising biomarker of hippocampal and cortical network disinhibition and hyperexcitability in APP/PS1 mice, with potential value as an early disease marker in Alzheimer's disease." (PMID 41293234, 2025). "A mixture of indole, indole-3-acetic acid, and IPA upregulated the expression of AhR, decreased the NF-κB and generation of the NLRP3 inflammasome, and lowered the level of proinflammatory cytokines in APP/PS1 mice, a mouse model of Alzheimer’s disease (AD)." (PMID 40942152, 2025). "Abnormal processing of amyloid precursor protein (APP) results in amyloid beta peptide (Aβ), a pathological marker in Alzheimer’s disease." (PMID 40144551, 2025). "Amyloid precursor protein (APP), which has primarily been studied in Alzheimer’s disease, is gaining recognition for its role in tumor growth and survival." (PMID 41614805, 2025). "The fact that cellular iron levels directly control APP translation through IREs found in the 5’UTR mRNA suggests a significant connection between iron homeostasis and Alzheimer’s disease." (PMID 40438504, 2025). "For example, Alzheimers disease is described to accumulate Tau-containing neurofilaments and Beta-amyloid plaques formed from APP (Amyloid Precursor Protein)." (PMID 40589526, 2025). "Trisomy 21 (T21) confers increased gene dosage of the amyloid precursor protein (APP) and other proteins (BACE2, S100β, DYRK1A, RCAN1) involved in Alzheimer's disease (AD) pathology." (PMID 40536124, 2025). "By using adeno‐associated viruses, we overexpressed Hevin in hippocampal astrocytes of middle‐aged APP/PSEN mice, an established Alzheimer's disease (AD) model." (PMID 39935382, 2025). "Previously, we discovered that Vim exhibits fragmented bands in the AEP-activated state in the brains of both APP/PS1 mice and Alzheimer’s disease (AD) patients." (PMID 40243407, 2025).